CX3CR1 (C-X3-C motif chemokine receptor 1)
Description:
Receptor for the C-X3-C chemokine fractalkine (CX3CL1) present on many early leukocyte cells; CX3CR1-CX3CL1 signaling exerts distinct functions in different tissue compartments, such as immune response, inflammation, cell adhesion and chemotaxis. CX3CR1-CX3CL1 signaling mediates cell migratory functions (By similarity). Responsible for the recruitment of natural killer (NK) cells to inflamed tissues (By similarity). Acts as a regulator of inflammation process leading to atherogenesis by mediating macrophage and monocyte recruitment to inflamed atherosclerotic plaques, promoting cell survival (By similarity). Involved in airway inflammation by promoting interleukin 2-producing T helper (Th2) cell survival in inflamed lung (By similarity). Involved in the migration of circulating monocytes to non-inflamed tissues, where they differentiate into macrophages and dendritic cells (By similarity). Acts as a negative regulator of angiogenesis, probably by promoting macrophage chemotaxis. Plays a key role in brain microglia by regulating inflammatory response in the central nervous system (CNS) and regulating synapse maturation (By similarity). Required to restrain the microglial inflammatory response in the CNS and the resulting parenchymal damage in response to pathological stimuli (By similarity). Involved in brain development by participating in synaptic pruning, a natural process during which brain microglia eliminates extra synapses during postnatal development (By similarity). Synaptic pruning by microglia is required to promote the maturation of circuit connectivity during brain development (By similarity). Acts as an important regulator of the gut microbiota by controlling immunity to intestinal bacteria and fungi (By similarity). Expressed in lamina propria dendritic cells in the small intestine, which form transepithelial dendrites capable of taking up bacteria in order to provide defense against pathogenic bacteria (By similarity). Required to initiate innate and adaptive immune responses against dissemination of commensal fungi (mycobiota) component of the gut: expressed in mononuclear phagocytes (MNPs) and acts by promoting induction of antifungal IgG antibodies response to confer protection against disseminated C.albicans or C.auris infection. Also acts as a receptor for C-C motif chemokine CCL26, inducing cell chemotaxis. [Isoform 1]: (Microbial infection) Acts as a coreceptor with CD4 for HIV-1 virus envelope protein. [Isoform 2]: (Microbial infection) Acts as a coreceptor with CD4 for HIV-1 virus envelope protein. May have more potent HIV-1 coreceptothr activity than isoform 1. [Isoform 3]: (Microbial infection) Acts as a coreceptor with CD4 for HIV-1 virus envelope protein. May have more potent HIV-1 coreceptor activity than isoform 1.
Synonyms: CMKBRL1; GPR13; CMKDR1; V28; CCRL1; GPRV28
Tractability: Small molecule: a structure with a bound ligand is known; a high-quality ligand is known; it belongs to a druggable protein family. Antibody: UniProt places it where antibodies can reach, with high confidence; its Gene Ontology location is reachable by antibodies, with high confidence; UniProt predicts a signal peptide or a membrane-spanning region; the Human Protein Atlas places it where antibodies can reach. PROTAC: its protein half-life has been measured; a small molecule that binds it is known.
Target class: Peptide receptor (family A GPCR); Family A G protein-coupled receptor; Chemokine receptor; CX3C chemokine receptor; Membrane receptor
Chemical probes: KAND567 (high quality)
Gene: Protein-coding gene on chromosome 3 (39,263,495 to 39,281,735, reverse strand). Ensembl gene ENSG00000168329.
Subcellular location: Cell membrane
Subcellular location (Human Protein Atlas): Plasma membrane
Pathways (Reactome):
Disease: RSV-host interactions; Respiratory syncytial virus (RSV) attachment and entry
Signal Transduction: Chemokine receptors bind chemokines; G alpha (i) signalling events
Gene Ontology:
Molecular function: C-X3-C chemokine binding; C-X3-C chemokine receptor activity; CX3C chemokine receptor binding; protein binding; C-C chemokine binding; C-C chemokine receptor activity; chemokine receptor activity; G protein-coupled peptide receptor activity; G protein-coupled receptor activity; cytokine receptor activity
Biological process: antifungal innate immune response; cell adhesion; chemotaxis; adaptive immune response; autocrine signaling; brain development; calcium-mediated signaling; cell chemotaxis; cell-cell signaling; cellular defense response; cellular response to lipopolysaccharide; central nervous system maturation; G protein-coupled receptor signaling pathway; host-mediated modulation of intestinal microbiota composition; immune response; innate immune response; leukocyte chemotaxis; leukocyte tethering or rolling; microglial cell activation involved in immune response; modulation of chemical synaptic transmission; multiple spine synapse organization, single dendrite; negative regulation of apoptotic signaling pathway; negative regulation of hippocampal neuron apoptotic process; negative regulation of interleukin-1 beta production; negative regulation of microglial cell mediated cytotoxicity; and 20 more
Cellular component: cell surface; plasma membrane; dendritic tree; external side of plasma membrane; macropinosome membrane; neuron projection; neuronal cell body membrane; perinuclear region of cytoplasm; membrane
Genetic constraint (gnomAD): Loss-of-function variants: 0 observed, 1.92 expected, observed/expected ratio (o/e) 0, 90% interval 0 to 1.38. That is too few expected variants to judge how well the gene tolerates losing a copy. Missense variants: 363 observed, 456.13 expected, observed/expected ratio (o/e) 0.8, 90% interval 0.73 to 0.87. Synonymous variants: 168 observed, 188.51 expected, observed/expected ratio (o/e) 0.89, 90% interval 0.79 to 1.01.
Homologues: Orthologues: chimpanzee CX3CR1 (98% identical), macaque CX3CR1 (95% identical), dog CX3CR1 (84% identical), rabbit CX3CR1 (84% identical), guinea pig CX3CR1 (83% identical), mouse Cx3cr1 (83% identical), rat Cx3cr1 (82% identical), pig CX3CR1 (80% identical). Paralogues in human: CCR2 (41% identical), CCR4 (41% identical), CCR1 (39% identical), CCR5 (39% identical), CCR3 (37% identical), CCR8 (37% identical), ACKR2 (34% identical), CCR7 (32% identical), CCR6 (31% identical), ACKR4 (31% identical), CXCR3 (30% identical), CXCR2 (30% identical), and 11 more.
Diseases named in the same sentence as CX3CR1 in open-access papers:
CX3CR1 is named in the same sentence as 415 diseases in open-access papers, as found by Europe PMC text mining. Sharing a sentence is not in itself a finding about the gene and the disease. The quoted sentences say what the papers report.
atherosclerosis (114 papers, 2005 to 2025). A disease characterized by the build-up of fatty material and calcium deposition in the arterial wall resulting in partial or complete occlusion of the arterial lumen. "The CX3CL1/CX3CR1 axis has been implicated in the development of atherosclerosis and cardiovascular disease, but until now, scarce data are available regarding the influence of the CX3CL1/CX3CR1 axis in familial combined hyperlipidaemia (FCH)." (PMID 41153665, 2025). "For example, this study has demonstrated that shear stress induces VCAM-1 via the NF-κB pathway in vascular endothelial cells, thereby upregulating the expression of CX3CR1—a process closely associated with the development of atherosclerosis." (PMID 41282026, 2025). "At the genetic level, the CX3CR1 gene has been shown to be associated with atherosclerosis in BD patients via vascular inflammation injury." (PMID 41141090, 2025). "The 249I allele carriers of the CX3CR1 V249I polymorphism had a reduced risk of atherosclerosis and coronary artery disease in the heterozygous state." (PMID 40508161, 2025). "Since the CX3CL1/CX3CR1 axis is primarily expressed on endothelial and cardiac cells, it has been implicated in the athogenesis of diseases such as atherosclerosis and heart failure." (PMID 40936920, 2025). "CX3CR1 is well known to be associated with atherosclerosis and vascular inflammation and is also involved in the monocyte-endothelial interaction and enables leukocytes to crawl along the blood vessels." (PMID 38609887, 2024). "Monocytic CX3CR1 is known to be associated with atherosclerosis and vascular inflammatory processes, and increased expression levels of CX3CR1 on classical and intermediate monocytes (IMs) have recently been observed in patients with obesity." (PMID 38175171, 2024). "CX3CR1 is associated with atherosclerosis and vascular inflammatory processes and contributes to the accumulation of tumor-associated macrophages in patients with skin cancer." (PMID 38175171, 2024). "Polymorphisms in the Cx3cl1 receptor, Cx3CR1, have been identified as genetic risk factors for atherosclerosis, and the deletion of Cx3cl1, Cx3CR1 and Cxcl1 suppresses atherogenesis." (PMID 38473793, 2024). "In CX3CR1‐deficient mice, the CX3CL1/CX3CR1 axis is involved in the progression of atherosclerosis, as CX3CR1 deficiency reduces lesion formation in atherosclerosis." (PMID 37452512, 2023). "Correspondingly, CX3CR1 is also associated with atherosclerosis and vascular inflammatory processes." (PMID 36921085, 2023). "Circulating monocytes from suPARTg mice also exhibited increased expression of C-X3-C motif chemokine receptor 1 (CX3CR1), another chemokine receptor that has been implicated in atherosclerosis, compared with WT." (PMID 36194491, 2022). "Inflammatory monocytes produce pro-inflammatory cytokines, reactive oxygen species (ROS), and express vascular homing molecules, including CX3CR1 and CD11a, indices that have been associated with the development of atherosclerosis." (PMID 31040846, 2019). "In a study that first reported on the kidney function of a general population, CX3CR1 rs3732379 SNP was associated with atherosclerosis of the coronary artery, SHROOM3 rs17319721 and PIP5K1B rs4744712 were associated with kidney disease." (PMID 29016630, 2017). "The chemokine receptor CX3CR1 has been implicated as an attractive therapeutic target in several diseases, including atherosclerosis and diabetes." (PMID 26656484, 2016). "Fractalkine (CX3CL1) and its receptor, CX3CR1, which are expressed in human plaques, had been implicated in atherosclerosis." (PMID 26688689, 2015). "In particular, CX3CR1 has been implicated in the pathogenesis of rheumatoid arthritis, glomerulonephritis, atopic dermatitis, psoriasis, Crohn's disease and atherosclerosis." (PMID 26035381, 2015). "Deficiency of the chemokine receptor CX3CR1, a regulator of monocyte adhesion and migration, decreases DC accumulation in the arterial wall leading to reduced atherosclerosis." (PMID 22347402, 2012).
atherosclerosis (continued). "Deficiency of the fractalkine receptor CX3CR1 resulted in decreased atherosclerosis and a decreased number of DCs in atheromas." (PMID 21658276, 2011). "In a meta-analysis of genetic polymorphisms of CX3CR1, 280M allele carriers of the CX3CR1 T280M polymorphism had a reduced risk of atherosclerosis and coronary artery disease in the heterozygous state but an increased risk of ischemic cerebrovascular disease in the homozygous state." (PMID 40508161, 2025). "CX3CR1 is well known to be associated with atherosclerosis and vascular inflammation." (PMID 38172514, 2024). "Similarly, in PLWH, the intermediate monocyte counts were associated with subclinical atherosclerosis and the expression of CX3CR1 on CD16+ monocytes independently predicted carotid artery thickness." (PMID 38247848, 2024). "CMV-specific CD4+ T cells expressing CX3CR1 are linked to atherosclerosis, and treatments targeting CMV may impact CVD outcomes." (PMID 39000373, 2024). "Therefore, it is clear that FKN and CX3CR1 must play important roles in the pathogenesis of atherosclerosis and can be potentially used to assess cardiovascular risk in patients." (PMID 37510939, 2023). "In a mouse model of CKD, atherosclerosis was attenuated in CX3CR1-deficient animals." (PMID 34163473, 2021). "Importantly, animal and human data have also suggested a specific role for CX3CR1 expression by T-cells in CKD-associated acceleration of atherosclerosis." (PMID 34163473, 2021). "This elegant work demonstrated less severe atherosclerosis with reduced monocyte survival and increased apoptotic monocytes within atherosclerotic plaques of CX3CR1-deficient mice - effects that were reversed by enforced expression of the anti-apoptotic protein Bcl-2." (PMID 34163473, 2021). "In addition, it has been showed that the fractalkine receptor CX3CR1 plays a key role in atherosclerosis, and that a polymorphism in its gene is associated with a reduced risk for CAD." (PMID 33066277, 2020). "In addition, the expression of CX3CR1 was reported on CMV-specific CD4+ T cells in patients showing HIV-associated atherosclerosis." (PMID 29915583, 2018). "Also for CX3CR1-deficient mice, it was observed that these animals have reduced atherosclerosis development, implicating CX3CR1 in atherogenesis." (PMID 26257740, 2015). "Epidemiological human studies revealed that decreased activity of the CX3CL1/CX3CR1 pathway due to genetic factors may be associated with a lower risk of atherosclerosis as well as a decreased incidence in the episodes of plaque destabilization." (PMID 25959742, 2015). "However, some evidence suggests that CX3CR1 is as well implicated in atherosclerosis by recruiting monocytes into the lesion, as recently confirmed by Cx3cr1 depletion which impairs DC as well as macrophage accumulation in aortic lesion, thus resulting in reduced atherosclerotic plaque." (PMID 35966516, 2022). "IL-15 can exacerbate atherosclerosis by promoting cytotoxic capacity, CX3CR1-dependent vascular-homing, and increasing CD2 expression." (PMID 40454002, 2025). "Given that CD8 T cells expressing CX3CR1 are predominantly cytotoxic, CX3CR1/CX3CL1 interactions in atherosclerosis are likely pathological." (PMID 40454002, 2025). "BI665088, a nano-antibody by AblynxTM in partnership with Boehringer IngelheimTM, inhibited atherosclerosis development in human CX3CR1-expressing mice at 30 mg/kg." (PMID 41269996, 2025). "The role of the CX3CL1/CX3CR1 axis in atherosclerosis and cardiovascular disease has been demonstrated in different studies." (PMID 41153665, 2025). "One of the axes implicated in the development of atherosclerosis and cardiovascular disease is the CX3CL1/CX3CR1 axis." (PMID 41153665, 2025). "CX3CL1/CX3CR1 promotes monocyte recruitment and inflammatory cytokine release in atherosclerosis and contributes to the development of atherosclerosis at various stages, including vascular smooth muscle cell migration and angiogenesis." (PMID 40508161, 2025).
atherosclerosis (continued). "The recruitment of CX3CR1+ monocytes and cytotoxic T cells can lead to an inflammatory environment, a phenomenon observed in conditions like atherosclerosis." (PMID 40861638, 2025). "Inhibition of CX3CR1 in animal models has been shown to lead to the prevention of atherosclerosis, showing a dramatic reduction in plaque size and composition, consistent with more stable features." (PMID 41153665, 2025). "V249I and T280M polymorphisms of CX3CR1 protein form a common I249M280 and are related to a reduced risk of acute coronary events and atherosclerosis and with a lowered endothelial reactivity." (PMID 38674114, 2024). "Through the method of bioinformatics, we finally obtained 10 hub genes in atherosclerosis and metabolic syndrome, and selected 3 of the most significant genes (CX3CR1, IL32, TLR5) for blood PCR verification." (PMID 39095691, 2024). "CX3CL1 and its receptor CX3CR1 were discovered more than twenty years ago, and a large amount of evidence has emerged linking the CX3CL1–CX3CR1 axis to various diseases, such as atherosclerosis, allergic diseases, neurodegeneration, and cancers." (PMID 38674036, 2024). "Recent studies have indicated that CX3CR1 participates in the development and regulation of atherosclerosis." (PMID 38505607, 2024). "Targeting CD4+ T‐cell activation and CX3CR1+ polarization has the potential to attenuate atherosclerosis in PD patients." (PMID 38979792, 2024). "Clinically, the substantial increases in CX3CR1+/CD4+ T‐cells observed here are of particular note since inhibition of CX3CR1 to ameliorate atherosclerosis progression is promising, as is CX3CR1 modulation in the treatment of CKD." (PMID 38979792, 2024). "CKD+PD mice had more vascular homing (CX3CR1+) T‐cells, a subtype reported to target and infiltrate the aortic wall to aggravate atherosclerosis." (PMID 38979792, 2024). "PD polarized CD4+ T‐cells toward an inflammatory Th1/Th17 phenotype, and increased CX3CR1+ CD4+ T‐cells, which are associated with vascular homing in CKD‐associated atherosclerosis." (PMID 38979792, 2024). "Of relevance, sulfated proteins include several chemokine receptors (e.g., CCR2, CCR5, CX3CR1) and adhesion molecules (e.g., PSGL1), which are implicated in atherosclerosis." (PMID 37424015, 2023). "CXC-motif chemokine receptor-4 (CXCR4), CC chemokine receptor 2 (CCR2), and C-X3-C Motif Chemokine Receptor 1 (CX3CR1) accelerate atherosclerosis by promoting vascular inflammation." (PMID 37342437, 2023). "CCR2, CCR5 and CX3CR1 are all involved in the recruitment of monocytes in the pathological process of atherosclerosis." (PMID 37180791, 2023). "CX3CR1 participates in numerous physiological processes and is involved in many important human diseases, such as atherosclerosis, rheumatoid arthritis, neurodegenerative diseases, and cancer, making it an attractive therapeutic target." (PMID 35767622, 2022). "Adoptive transfer of CX3CR1+ T-cells restored atherosclerosis progression in mice with renal impairment, suggesting a specific contribution of CX3CR1+ T-cells to atherosclerosis in setting." (PMID 34163473, 2021). "CX3CL1 upregulation has also been observed in macrophage-rich human coronary artery plaques and several studies have demonstrated that genetic deletion of either CX3CL1 or CX3CR1 protects mice against atherosclerosis." (PMID 33503867, 2021). "Meanwhile, CX3CR1 can bind to fractalkine (FKN; also known as CX3CL1) and modulate the secretion of insulin and atherosclerosis associated with insulin resistance." (PMID 34269146, 2021). "A 30mg/kg dose of this “nanobody”, named BI665088, which was developed by AblynxTM in collaboration with Boehringer IngelheimTM was shown to inhibit atherosclerosis development in mice with knock-in human CX3CR1 expression." (PMID 34163473, 2021). "During atherosclerosis, monocytes expressing CX3CR1 bind and adhere to the endothelium, which expresses mCX3CL1." (PMID 33503867, 2021).